MX1 (MX dynamin like GTPase 1)
Diseases named in the same sentence as MX1 in open-access papers (continued):
Sharing a sentence is not in itself a finding about the gene and the disease.
lupus (21 papers, 2005 to 2025). "We used the pristane-induced lupus model in C57BL/6 mice carrying an intact Mx1 allele (B6.A2G-Mx1) and B6.A2G-Mx1-Ifnlr1−/− mice deficient in functional IFN-λ receptors." (PMID 34769174, 2021). "In patients with systemic lupus erythematosus, overexpression of MX1 may be associated with accelerated atherosclerosis." (PMID 40809841, 2025). "This is consistent with other studies that have shown the implication of ISG15 and MX1 in the progression of lupus and some of its crucial pathological events, such as lymphocytopenia and lupus nephritis." (PMID 40574053, 2025). "Several studies revealed that the level of MX1 protein in the lysates of mononuclear cells from the peripheral blood of patients with systemic lupus erythematosus was markedly elevated compared to the normal controls." (PMID 38972952, 2024). "In our immune-histochemical detection results of lupus mice, MX1 also showed a tendency to increase, Therefore, the importance of mx1 in the pathogenic mechanism of lupus nephritis cannot be ignored." (PMID 39301055, 2024). "It is reported that systemic lupus erythematosus patients with elevated MX1 levels exhibit declines in vascular reactivity." (PMID 37662558, 2023). "Meanwhile, the expression levels of IFN-I signature genes (ISGs), such as Mx1, Irf7, Oas1, and Isg15, were increased in the renal tissues of KI lupus mice compared with WT lupus mice." (PMID 35788118, 2022). "Our data on MX1 and ISGs are in line with the literature where splenocytes from lupus-prone mice treated with tofacitinib (10 mg/kg daily) showed also decreased expression of MX1 and ISGs in comparison to untreated control animals." (PMID 34020693, 2021). "Additionally, MX1 expression was upregulated in pristine‐induced lupus mice." (PMID 37506140, 2023). "Because ISG expression reflects serum IFN-I levels, we compared surface CD64 levels on monocytes with the transcript levels of three ISGs (MX1, IFI44, and Ly6E) in PBMCs from lupus patients (n = 108)." (PMID 20478071, 2010). "In the present report, RhoA mRNA expression further is shown to be higher in the PBMCs of lupus patients when compared to healthy controls, and expression levels correlate positively with type I IFN scores and interferon-induced genes, including CXCL10, OAS1, IFIT3, and MX1." (PMID 38243295, 2024). "In our project,RhoA mRNA expression further has been shown to be higher in the PBMCs of lupus patients when compared to healthy controls, and expression levels correlate positively with type I IFN scores and interferon-induced genes, including CXCL10, OAS1, IFIT3 and MX1." (PMID 37790522, 2023).
HIV-1 infection (20 papers, 2009 to 2025). The type species of lentivirus and the etiologic agent of acquired immunodeficiency syndrome (AIDS). "Infection by HIV-1 CH042 constructs containing the AxxA or R191A mutation in Nef was associated with ~2-fold higher mRNA expression levels of the IFN-stimulated gene (ISG) MX1 encoding myxoma resistance protein 1 (Mx1), compared to WT HIV-1 infection." (PMID 41354661, 2025). "As controls, we used parental THP-1 cells, as well as the CRISPR/Cas9 control (Cntrl) cells, which had similar permissivity to HIV-1 infection and expressed comparable MX1 and MX2 levels after IFN-α stimulation." (PMID 27279606, 2016). "Here, we performed structure-function studies to investigate the requirements for oligomerization of both MX2 and chimeric MX1(NMX2) for the inhibition of HIV-1 infection." (PMID 26446602, 2016). "Additionally, MX1 is found to be associated with HIV total DNA and MX2 can be involved in the innate immune response to HIV-1 infection." (PMID 41226717, 2025). "No changes were found at mRNA expression levels of ISG15 and MX1 after HIV-1 infection." (PMID 41041557, 2025). "Furthermore, sustained upregulation of this ISG cluster, including ISG15, MX1, OAS1 and STAT1, is a hallmark of untreated HIV-1 infection." (PMID 41226717, 2025). "For the validation of the gene expression results and to confirm that the higher expression of these molecules was associated with uncontrolled HIV-1 infection, mRNA levels for PARP9, MX1 and USP18 were validated in independent cohorts of HIV-1 infected individuals." (PMID 32760119, 2020). "In addition, significant changes were observed in the expression of coding genes involved in the host response to infection (e.g., ISG15, STAT1, OAS3, ISG20, CCL2, and MX1), confirming robust HIV-1 infection of these cells." (PMID 31551335, 2019). "On the other hand, HIV-1 infection triggers the over-expression of several RFs genes, including IFITM1, IFITM2, IFITM3, MX1, MX2, TETHERIN, IFN1a, and IFNR." (PMID 39476027, 2024). "Here, we performed site-directed mutagenesis studies to investigate in detail the importance of oligomerization for the inhibition of HIV-1 infection in the context of both human MX2 and the MX1(NMX2) chimera." (PMID 26446602, 2016). "We observed an increase in the levels of various ISGs such as MX1, IFI44L, DDX58, RSAD2, and several of the IFITs, which have been shown to play an important role against HIV-1 infection in MDMs." (PMID 25170834, 2014). "In primary myeloid cells, both HIV-1 infection and the viral accessory protein Vpr have been shown to activate this pathway, resulting in increased STAT1 phosphorylation together with coordinated induction of ISG15, MX1, IFIT3/IFI44L, and OAS genes." (PMID 41226717, 2025). "The observation that these mutants, together with F602D, retain full antiviral activity provides strong evidence that higher-order oligomerization is not required for the inhibition of HIV-1 infection by MX1(NMX2)." (PMID 26446602, 2016). "To gain further insight into this issue, we performed spreading HIV-1 infection experiments in the presence of MX2, MX2 (GMX1), or MX1 (as negative control) alone or together with the short isoform of MX2." (PMID 31722207, 2019). "We observe very similar elevations of MX1; however, MX1, in contrast to MX2, has not been shown to restrict HIV-1 infection, and a comparative analysis in humanized mice has not been previously performed." (PMID 30867315, 2019).
hepatoma (14 papers, 2010 to 2025). "To confirm the biological IFN activity of each sample, we stimulated the human hepatocellular carcinoma cell line, HepG2, with PASC patient serum and investigated the mRNA expression level of IFN-stimulated genes (ISGs) involving Mx1, ISG15, PKR, and IFIT1." (PMID 39921694, 2025). "To this end, we compared the expression of twelve genes either linked to the induction of innate immunity (STAT1, STAT2, PKR) or IFN effector genes (OAS1/2, IFIT1–3, RSAD2, MX1, TRIM14, ISG15) in HCV-infected hepatoma cells and mature iHLCs." (PMID 29497123, 2018). "In agreement with the previous reports, IFN-αinduced expression of ISGs, such as of Mx1 and OAS1, in the chicken hepatoma cells required HDAC activity." (PMID 24068929, 2013). "Human hepatoma cells and primary murine hepatocytes were treated with TNF-α/LPS/IL-6/IL-10 and USP18, phosphorylated (p)-STAT1 and myxovirus (influenza virus) resistance 1 (Mx1) expression was determined." (PMID 27009955, 2016).
co-infection (12 papers, 2008 to 2025). "The co-infection allowed observation of multiple genes involved in the obstruction of the viral life cycle within the host such as MX1,MX2, OASL, OAS2, heat shock protein family A (Hsp70) member 8 (HSPA8), and radical S-adenosyl methionine domain containing 2 (RSAD2)." (PMID 33187194, 2020). "An early and enhanced upregulation of IFN-induced antiviral gene expression (indicated by RIG-I, IFN-β-1, Mx1, and IFITM1) was observed in A549 cells for the treatment with DIPs only and the co-infection with RSV in comparison to infection with RSV only." (PMID 37766278, 2023). "Notably, Several genes, such as FASLG, MX1, and GBP, exhibit notable upregulation under co-infection conditions, suggesting a heightened oxidative stress response or immune activation." (PMID 39770656, 2024). "Our results showed that IFN1, Mx-1, ISG15, and VIG1 are significantly elevated in co-infection, which indicated that IHNV and IPNV co-infection could induce stronger antiviral responses." (PMID 36016354, 2022).
HCMV infection (12 papers, 2014 to 2025). "HCMV infection led to a moderate induction of MX1, IFIT3, and ISG15, compared to the mock infected cells, as expected." (PMID 37376632, 2023). "The induction of Mx1 was abrogated in CHX-ActD treated cells, showing that the induction of this protein following HCMV infection depended on the expression of interferons and on interferon signaling." (PMID 40143353, 2025). "The induction of ISGs Mx1 and ISG15 was markedly enhanced following HCMV infection of HFF ko-SQSTM1 cells compared to controls." (PMID 39339916, 2024). "Inhibition of CXCL10, MX1, and OAS1 by UL23 at late times after HCMV infection was observed in this study, so UL23 protects HCMV against the immunomodulatory and antiviral responses of IFN-I." (PMID 34305856, 2021). "Literature suggests that several ISGs, including MX1 and ISG15, have been found to upregulated after human cytomegalovirus (HCMV) infection and behave in an interferon-independent, IRF3-dependent manner." (PMID 33419081, 2021). "Several ISGs, including IFIT1, IFIT2, IFIT3, Mx1, Mx2, CXCL10 and ISG15 were found to be upregulated transcriptionally following HCMV infection independently of type I IFN-initiated JAK-STAT signaling, but dependent on intact IRF3 signaling." (PMID 30871003, 2019). "In the context of the HCMV infection, Ashley and colleagues demonstrated that the promoters of several core IRGs, including IFIT1, IFIT3, MX1, and ISG15, are transcriptionally induced by the activation of the transcription factor IRF3 and therefore function independent of the IFN responses." (PMID 36552792, 2022). "To gain further insight into the role of these genes during HCMV infection, we measured virus production in HCMV-infected HFFs after siRNA-mediated depletion of Mx1 or IFIT1—the latter having been shown to exert antiviral activity against HCMV only in fetal astrocytes upon lentiviral overexpression." (PMID 34162877, 2021). "Studies of HCMV infection in the presence of cycloheximide (CHX) have shown upregulation of IFIT1 (IFI56), IFIT2 (ISG54), IFIT3 (cig49, ISG60), MxA (the protein produced from the Mx1 gene) and ISG15." (PMID 30871003, 2019). "However, as with infection of MyD88-expressing cells, we observed that the UL88-STOP-mCh HCMV infection, in which MyD88 levels are higher, actually downregulated a number of antiviral ISGs, including IFITM1, IFITM2, IFITM3, MX1, and IFI16 (the nuclear sensor that plays a role in sensing of HCMV)." (PMID 40638072, 2025). "In contrast, upon infection with AD169ΔIE1, we observed a 6.3-, 3.5-, and 2.2-fold decrease in IFIT1, Mx1, and IFIT3 enrichment, respectively, which further supports the crucial role played by the IE1 protein in PAD-mediated citrullination during HCMV infection." (PMID 34162877, 2021). "Induction of the IFN-independent ISG viperin during HCMV infection is known to be induced by either IRF3 or IRF1, binding directly to its promoter, and this may also be the mechanism of IFIT1, IFIT2, IFIT3, CXCL10, Mx1, Mx2 and ISG15 upregulation." (PMID 30871003, 2019). "Nevertheless, MX1 was still significantly induced even in the absence of IFN signaling, which has not been broadly appreciated previously but has been shown in human fibroblasts upon HCMV infection." (PMID 37558422, 2023).
prostate carcinoma (12 papers, 2007 to 2024). A carcinoma that arises from epithelial cells of the prostate gland. "For example, deletion of Mx1 in prostate cancer is associated with a higher aggressive tendency and the expression of MxA is suppressed in a highly metastatic human prostate carcinoma cell line." (PMID 32967656, 2020). "Analysis of prostate cancer data sets in cBioPortal indicated that deletions were the most common genetic alteration in MX1 and were found in over 13% of patients." (PMID 39285636, 2024). "On the other hand, the gain of MX1 expression in in human prostate cancer LNCaP cells resulted in cell cycle arrest." (PMID 34361872, 2021). "Knockout of Mx1 in prostate cancer cells resulted in a lower sensitivity to the chemotherapeutic agent docetaxel compared to MxA-positive cells." (PMID 32967656, 2020). "Prostate cancer cells in which the Mx1 gene is knocked out have been shown to be much less sensitive to docetaxel compared with MxA-positive cells." (PMID 26411585, 2015). "It has been reported that the deletion of Mx1 gene, as a consequence of certain gene fusion events, is closely related to prostate cancer with a high aggressive tendency." (PMID 26411585, 2015). "However, MX1 in a prostate cancer study was found to be upregulated in ER stress pathway binding with heme-oxygenase (HO) as a downstream target in causing apoptosis in cancer cells." (PMID 39070493, 2024). "Real-time RT-PCR revealed GADD45A, MX1, EPB41L3/DAL1, and FBLN1 as generally downregulated in prostate cancer, whereas HOXB13 and EPB41L4B were upregulated." (PMID 17280610, 2007). "For example, the ISGs MX1 and MX2 show deep co-deletions in 14 % of prostate cancer patients." (PMID 27366948, 2016). "The analysis of individual genes by quantitative real-time PCR revealed that many (e.g. MX1, EPB41L3), but not all (notably BCCIP and TLR3) of the genes significant in the interaction analysis were also overexpressed generally in prostate cancers compared to benign tissues." (PMID 17280610, 2007).
autoimmune disease (10 papers, 2006 to 2024). A disorder resulting from loss of function or tissue destruction of an organ or multiple organs, arising from humoral or cellular immune responses of the individual to their own tissue constituents. "Expect for LN, MX1 up-regulation also exists in rheumatoid arthritis, idiopathic interstitial pneumonia, alopecia areata and other autoimmune diseases." (PMID 35047003, 2021). "We have also shown evidence for induction of the MX1 gene product, p78MX1, in lesional hair follicle tissue of a sporadic case of alopecia areata, an autoimmune disorder that has an elevated frequency in DS." (PMID 16539728, 2006). "In addition, our meta-analysis revealed sex- and age-related CD4+ T cell changes, with new observations such as increased Tnaive MX1 and Tem (Tph) in females, potentially contributing to gender differences in autoimmune disease incidence." (PMID 38359792, 2024). "Additionally, other genes that were identified in our study, including BCL2, OAS1, MX1, and SKP2 have been previously associated with various autoimmune diseases." (PMID 29387060, 2017). "In SIgAD patients with concomitant autoimmune diseases, decreased expression levels of genes related to the type I interferon (IFN) pathway, including IFIT1, MX1, IFI6, and IFI44L, were observed." (PMID 38474381, 2024). "MX1 and OAS2 were also detected in the blood of patients with an autoimmune disease, namely systemic lupus erythematous disease, in which their roles were not totally defined." (PMID 30374345, 2018).
dermatomyositis (9 papers, 2020 to 2026). Dermatomyositis (DM) is a type of idiopathic inflammatory myopathy characterized by evocative skin lesions and symmetrical proximal muscle weakness. "Evidence suggests that MX1 is consistently elevated in affected muscle tissue in IIM, particularly dermatomyositis, where it demonstrates high tissue specificity, though its expression is not exclusive to this subtype." (PMID 41769532, 2026).
lung carcinoma (9 papers, 2015 to 2025). "Several studies have demonstrated the combination of eribulin and cisplatin to be effective in treating ovarian cancer (A2780) and TNBC (HCC1806 and MX-1), as well as advanced solid tumors (breast, pancreatic, bladder, head and neck, and lung cancer)." (PMID 35454385, 2022). "Our in vitro data are consistent with in vivo animal studies that oral apoA-I mimetic peptides upregulate in vivo IFNβ1 and MX1 levels in the lungs of mice with lung cancer." (PMID 34494942, 2021). "In our study we observed that SARS-CoV-2 infection of the lung carcinoma epithelial cell line Calu-3 triggers IL-6 expression while was unable to induce Mx1 gene expression, suggestive of a strong reduction of type I IFN production and, thus, confirming what already observed." (PMID 34473805, 2021).
psoriasis (9 papers, 2010 to 2025). An autoimmune condition characterized by red, well-delineated plaques with silvery scales that are usually on the extensor surfaces and scalp. "In addition, MX1 has been considered to be important antiviral proteins, which was found that up-regulated in psoriasis lesions in this study." (PMID 40560938, 2025). "ISG15, MX1, IFI44L, and IFI27 were the characteristic psoriasis genes found in suprabasal keratinocytes." (PMID 36172384, 2022). "ISG15, MX1, IFI44L, and IFI27 were the characteristic genes of psoriasis in suprabasal keratinocytes." (PMID 36172384, 2022). "In addition, 8 genes (DEFB103A, OASL, HERC6, ISG15, MKI67, MX1, MXD1, SCO2) were considered to have statistically significant differences in sensitivity of short-term treatment for psoriasis." (PMID 40560938, 2025). "All other DEGPs could be placed along a continuum, with some showing greater psoriasis specificity (e.g., DBI, GLTP, HRNR, KRT73, ELOVL7), and others showing similar expression shifts in many or most skin diseases (e.g., MX1, S100A8, S100A9, STAT1, LAP3)." (PMID 26251673, 2015). "The list of the DEG in common in the 4 studies contains many genes known to be upregulated in psoriasis, such as IFNγ-regulated genes STAT-1, STAT-3 and MX1; antimicrobial peptides (beta defensin 4, lipocalin 2, S100A7); and pro-inflammatory proteins such as IL-8, CXCL1, IL-1F9, TNFSF10/TRAIL." (PMID 20422035, 2010). "In contrast, antiviral genes MX1, OAS3, and IFI44L were suppressed in γδ T cells in psoriasis, suggesting that these cells may be less primed to combat viral threats; alternatively, this finding could reflect an upregulation of these genes within the control group." (PMID 41181116, 2025). "One can observe that the top psoriasis genes, including IFNg genes OASL, MX1; IL17-regulated CCL20 and IL19 are not different in the PPPP/PPP as compared with normal acral skin." (PMID 27152848, 2016).
avian influenza (8 papers, 2013 to 2025). Infection of domestic and wild fowl and other birds with influenza A virus. "MX1 is an antiviral gene and has been shown to have a role in avian flu resistance." (PMID 35052428, 2021).
glioma (7 papers, 2017 to 2025). A benign or malignant brain and spinal cord tumor that arises from glial cells (astrocytes, oligodendrocytes, ependymal cells). "C4 MX1+ Glioma cells showed enrichment in immune responses to viruses and symbionts, as well as in regulating viral processes and negative regulation." (PMID 39403379, 2024). "We classified the 40,650 astrocytomas obtained by Seurat and named the seven subclusters according to the marker genes as C0 IGFBP7+ Glioma cells, C1 OLIG2+ Glioma cells, C2 LINC02283+ Glioma cells, C3 LINC00632+ Glioma cells, C4 MX1+ Glioma cells, C5 FOSB+ Glioma cells, and C6 DLL3+ Glioma cells." (PMID 39403379, 2024). "The results showed that most of the astrocytoma subclusters had a higher percentage of G1 cell cycle, in addition, C0 IGFBP7+ Glioma cells and C4 MX1+ Glioma cells had a higher percentage of Group IV, suggesting that the malignant degree of cells in these two subclusters might be higher." (PMID 39403379, 2024). "Expression of ISGs MX1, XAF1, or OAS2 strongly correlated with MAP3K7 dependency in DepMap glioma lines and this correlation was still present, but weaker, in 930 non-glioma cell lines." (PMID 38632238, 2024).